EPHB2 (EPH receptor B2)
Diseases named in the same sentence as EPHB2 in open-access papers (continued):
Sharing a sentence is not in itself a finding about the gene and the disease.
cancer (92 papers, 2003 to 2025). A tumor composed of atypical neoplastic, often pleomorphic cells that invade other tissues. "The pro-apoptotic effect of EPHB2 knockdown further indicates its involvement in evading cell death, another key hallmark of cancer." (PMID 41322437, 2025). "EPHB2, a member of the Eph receptor family, is involved in cell-cell signaling and has been implicated in various cancers, including CRC." (PMID 40958237, 2025). "EPHB2 has been associated with cancer stemness and acquired sorafenib resistance via the β-catenin/TCF1 axis." (PMID 34987577, 2021). "To illustrate our approach, we applied this model to analyze the EphB2-ephrinB2 complex, which has been overexpressed and associated with multiple types of cancer, including prostate, gastric, colorectal and melanoma cancers." (PMID 33354416, 2020). "Previously, it was verified that EphB2 is a prognostic factor for several types of cancer; it has been associated with histological grade, stage, and overall and disease-free survival." (PMID 24959213, 2014). "A similar phenomenon has been described for EphB2, where the loss of expression was associated with cancer progression, and higher EphB2 expression was associated with prolonged survival." (PMID 19277044, 2009). "Ephrin receptor B2 (EPHB2) seems to be linked to genome instability, but its importance in cancer progression remains unclear." (PMID 40804837, 2025). "Furthermore, a loss of EphB2 expression was observed in the carcinomas of the obese mouse model, while in control mice EphB2 was more highly expressed in the normal mucosa." (PMID 38651144, 2024). "Other miRs have been linked to cancer stemness depending of the expression of certain tyrosine kinase receptors, such as EphB2 and EphA2, whose expression marks early and late CRC, respectively, EphB2 being a marker of staminality and EphA2 being expressed in the invasive CRC phase." (PMID 34065438, 2021). "A hypothesis that merits further investigation is that loss of EphB2 expression could be associated with better growth of cancer cells (hence the correlation between lower EphB2 levels and poorer RFS)." (PMID 34360867, 2021). "Phase 1 consisted of developing the machine learning model to identify potential protein–protein interface hotspots that could be viable as a drug target, using the cancer-associated EphB2-ephrinB2 protein complex (PDB code: 1KGY) for illustration." (PMID 33354416, 2020). "Some of the mutated genes, including the tyrosine kinases EPHA3 and EPHB2, are clearly amenable to pharmacological intervention and could represent novel therapeutic targets for these incurable cancers." (PMID 20838624, 2010). "In addition, EPHB2 is associated with mutations in multiple oncogenes and may promote the progression of malignant tumors through its interaction with the immune microenvironment." (PMID 41322437, 2025). "In addition, mutational inactivation of EPHB2 may also play an important role in cancer progression." (PMID 35223830, 2022). "As the overexpression of the EphB2-ephrinB2 complex is associated with these cancers, further analysis for drug discovery could aid in identifying possible new hotspots that potentially aid in drug discovery in the fight against cancer." (PMID 33354416, 2020). "In this study, the mRNA expression of EPHB2 across various cancers was analyzed and visualized using Timer2.0 based on data from the TCGA database." (PMID 41322437, 2025). "EphB2, a receptor tyrosine kinase, plays a central role in this process, exhibiting context-specific functions across different cancers." (PMID 40149421, 2025). "We next investigated ADCC caused by Eb2Mab-12-mG2a and Eb2Mab-12-hG1 against the endogenous EphB2-positive cancer cell lines in the presence of splenocytes derived from BALB/c nude mice." (PMID 40943224, 2025).
cancer (continued). "Recent pan-cancer studies reveal that molecular alterations like PLIN3/EPHB2 dysregulation and hypoxia-related signatures consistently promote M2 macrophage infiltration and immunosuppression, correlating with adverse outcomes across malignancies." (PMID 41220948, 2025). "Recent studies indicated that EPHB2 is involved in cellular proliferation, invasion, and resistance to anti-cancer immune responses, as well as M2 macrophage infiltration." (PMID 40804837, 2025). "We next confirmed the reactivity of Eb2Mab-12-mG2a and Eb2Mab-12-hG1 to CHO/EphB2 and endogenous EphB2-positive cancer cell lines." (PMID 40943224, 2025). "EphB2 is involved in malignant tumor progression through the promotion of invasiveness and metastasis." (PMID 40943224, 2025). "The observed inhibition of cell proliferation, migration, and invasion following EPHB2 knockdown, coupled with the induction of apoptosis, establishes EPHB2 as a critical regulator of multiple hallmarks of cancer." (PMID 41322437, 2025). "Eb2Mab-12 specifically reacted with the EphB2-overexpressed Chinese hamster ovary-K1 (CHO/EphB2) and some cancer cell lines in flow cytometry." (PMID 40943224, 2025). "Densitometric analysis further demonstrated that the increased EPHB2 protein expression in these cancer cell lines was statistically significant." (PMID 41322437, 2025). "A robust study evaluated the expression of EphB2 protein in a cohort of 138 different types of cancer." (PMID 39839790, 2024). "Mechanistically, EPHB2 regulates cancer stemness and drug resistance by driving the SRC/AKT/GSK3β/β-catenin signaling cascade." (PMID 36980210, 2023). "EPHB2 acts through driving Src/Akt/GSK3β/β-Catenin signaling cascades and regulates cancer stemness and drug resistance." (PMID 38259452, 2023). "High expression of EPHB2 is considered a proto-oncogene by promoting blood vessel formation by enhancing cancer cell motility, invasion, and metastasis." (PMID 36203528, 2022). "Firstly, we review the main biological features and the related signaling regulatory mechanisms of EphB2, and then we summarize the roles of EphB2 in cancer through current studies." (PMID 35223830, 2022). "To further characterize the genes used in the model, we performed differential pan-cancer analysis, showing that EPHB2 is most differentially and highly expressed in the vast majority of tumors." (PMID 36032135, 2022). "Regarding forward signaling by EphB2 in cancer cells, although the receptor is upregulated in most cancers, its response to ephrin is silent." (PMID 35223830, 2022). "Mechanistically, T cell factor-1 (TCF1) regulated the expression of EphB2 through promoter activation to form a positive Wnt/β-catenin feedback loop, thereby regulating cancer stemness and drug resistance." (PMID 35223830, 2022). "Several epigenetic modulators, such as VEGF (vascular endothelial growth factor), CXCR4 (CXC chemokine receptor 4), EPHB2 (EPH Receptor B2), miR-103, or any other sort of long non-coding RNAs, are carried by cancer-derived EVs to stimulate angiogenesis." (PMID 35159299, 2022). "Although studies have shown that EPHB2 is involved in the malignant progression of various cancers, its role in LUAD has yet to be investigated." (PMID 36032135, 2022). "In summary, these results on bidirectional signaling indicated that EphB2/ephrin has diverse and complex functions in different cancer types and surrounding environment." (PMID 35223830, 2022). "EPHB2 belongs to a member of the receptor tyrosine kinase family, and has been shown to act as an oncogene in various cancers." (PMID 34820156, 2021). "EPHB2 expression correlated with cancer progression, as the percentage of ratio of EPHB2 positive cells to the number of all cells was 28% in normal tissues, 40% in High Grade Squamous Intraepithelial Lesion tissues and 69.8% in SCCs." (PMID 34445116, 2021).
cancer (continued). "EPHB2 exhibited elevated expression in cancer NSCLC tissues, being correlated with increased depth of invasion, higher TNM stage, and decreased patient OS." (PMID 34445116, 2021). "In a previous work, we found that although EphB2 is expressed in normal and benign tissues, its levels in these tissues are lower than in cancer tissues." (PMID 34360867, 2021). "A similar trend towards co-expression of EphB2 and cognate ligands along cancer progression was also observed in cell lines." (PMID 34360867, 2021). "EPHB3 expression was higher in CRCs than in normal mucosa and was associated with the intestinal stem cell markers EPHB2, OLFM4, LRIG1, and a proposed cancer stem cell marker, CD44." (PMID 32294981, 2020). "Laz also inhibits cancer cell growth through inhibition of the phosphorylation of a receptor tyrosine kinase EphB2 that is often hyper-expressed in cancer cells; in addition to its ability to inhibit angiogenesis." (PMID 32221741, 2020). "Knockdown of ephrinB1 in SW480 and Hs578T human cancer cell lines suppresses RhoA activation by EphB2-Fc." (PMID 29059157, 2018). "Here, we show that the stimulation of ephrinB1 by EphB2-Fc promotes migration and invasion of cancer cells through RhoA activity." (PMID 29059157, 2018). "LGR5, EPHB2, CD44s and CD44v6 were all significantly up-regulated in cancer tissues compared to normal tissues (median increase 9.4-fold, 3.5-fold, 3.0-fold and 6.4-fold respectively, all p-values <0.0005; one-sample t-tests of logged values = 1)." (PMID 26367378, 2015). "Several target genes of miR-204, including HOXA10, MEIS1, FOXC1, MAP1LC3B, BCL2, NTRK2, SOX4 and EphB2, have been identified in different cancers." (PMID 26710269, 2015). "The results demonstrated that silencing EphB2 promoted cancer growth by stimulating cell proliferation through a mechanism of G1/S phase breakthrough, which was dependent on a cyclin D1/CDK6 cell cycle regulating signal." (PMID 24959213, 2014). "The mechanism of the higher expression of EphB2 acting as a predictive factor for QYHJ treatment arose as a result of the upregulation of EphrinB1, which stimulated the EphB2-expressing cells to inhibit cancer cell growth by downregulating the CDK6 expression." (PMID 24959213, 2014). "Some genes representing the KEGG pathway “Pathways in cancer” (Pdgfra, Pdgfrb, Vegfa, PPP3ca, EphB2 and Prkcn) and the gene ontology term “regulation of transmission of nerve impulses” (Bdnf, Ngfb, Klk8 and Edn1) were also included." (PMID 22384097, 2012). "Some of them, like Axl, EphB2, HGFR, and the nerve growth factor receptor TrkA are implicated in epithelial repair, proliferation, and cancer growth." (PMID 18167552, 2008). "EPHB2, identified as a predictive biomarker for immunotherapy response and survival across cancers, may modulate M2 macrophage polarization, linking their immunosuppressive functions to therapeutic resistance." (PMID 40165975, 2025). "Indeed, this has motivated some studies on the effect of drugs on cancer stem cells, in which EphB2 expression correlated with drug resistance in CRC cells." (PMID 38651144, 2024). "This is particularly important because EphB2 could aid in the identification of cancer stem cells and predict CRC relapse." (PMID 38651144, 2024). "Genes of WNT/β-catenin signaling and several stem cell signatures were predominantly ITH-low, but a small subset of genes in the LGR5 and EPHB2 cancer stem cell signatures had high scores, which contributed to the correlation of these signatures with PC1 of ITH-high genes." (PMID 38773143, 2024). "In cancer cells, EPHB2 may promote EMT, and in small extracellular vesicles, EPHB2 may promote angiogenesis, inducing ephrin-B reverse signaling, and STAT phosphorylation." (PMID 39228892, 2024). "In summary, EPHB2 can be used as a prognostic factor for this cancer." (PMID 39839790, 2024).
cancer (continued). "Finally, we provide our viewpoint on the future prospects of cancer research focusing on EphB2, especially with regard to the effects of EphB2 on tumoral immunity." (PMID 35223830, 2022). "Consequently, EphB2’s functional relevance and expression patterns in malignancies make this protein a potential prognostic biomarker and therapeutic target in cancer." (PMID 35223830, 2022). "In this review, we first systematically summarized and discussed the roles of EphB2 in cancer, as well as listed researches that may deepen our understanding of how it regulates cancer progression." (PMID 35223830, 2022). "Mutations on DEPTOR Tyr 289 have not been reported in cancer, whereas mutations within EPHB2 and SYK in various malignancies were described in multiple publications." (PMID 34634301, 2021). "Indeed, to aid in assessing the levels of EphB2 expression, we developed a scoring system with “non-cancer” tissues used as the baseline reference value (defined as 0)." (PMID 34360867, 2021). "In addition, nadolol, a beta blocker, has also been identified in this study to bind to the EphB2-ephrinB2 complex, and the possibility of this drug treating multiple cancers is still relatively unexplored." (PMID 33354416, 2020). "In addition to having anti–angiogenic activity, leading to cancer growth inhibition, azurin also inhibits cancer cell growth through interference with the phosphorylation of receptor tyrosine kinase EphB2 that is often hyper-expressed in cancer cells." (PMID 32221741, 2020). "Increases cancer stemness via modulation of the EphB2/EphA2 signaling in CRC CSc." (PMID 33489917, 2020). "We observed less obvious or partial effects of the same prohibitory small molecule and siRNAs in DU145 cells, and that might be due to a moderate gene expression pattern of Src and EphB2 pathways in this advanced cancer cell line." (PMID 31805710, 2019). "EphB2 is mainly participating in the phosphorylation of amino acid, protein kinase signal transduction of transmembrane receptor, nervous system development, and cancer progression." (PMID 31147453, 2019). "This down-regulation during cancer progression was also observed for EphB2." (PMID 20624275, 2010). "Previous studies have developed a peptide, monoclonal antibody or small molecule against EphB2 in an attempt to prevent its activation, which may be used as a potential treatment for cancer." (PMID 35223830, 2022). "Thus, in this paper we systematically summarize and discuss the roles of EphB2 in cancer." (PMID 35223830, 2022). "Hence, in the subsequent chapters we first review the main biological features and the related signaling regulatory mechanisms of EphB2, and then we summarize the roles of EphB2 in cancer through current studies, in order to provide some fundamental knowledge for following studies." (PMID 35223830, 2022). "For EPHB2, small-molecule inhibitors like STA-013, dasatinib and GLPG1790 (pan-Eph antagonist reducing cancer stem cells) are available, demonstrating antitumor effects in CRC and potential to modulate autoimmune inflammation." (PMID 40958237, 2025). "Eph receptor B2 (EphB2), an important member of the ephrin receptor family, can stimulate ABCG2 expression in other types of cancer cells, which can explain the correlation observed in our study." (PMID 39457707, 2024). "High expressions in EPHB2 and LGR5 signature cancer stem cells and low expressions on late transit amplifying colonic crypt genes were detected in RSS2." (PMID 38532103, 2024). "We have confirmed the correlation between IL-33 and markers like SerpinA1, SerpinA3, and EphB2 for SCC and Gli1, Gli2, FOXO3A for BCC as it highlights the complex interplay of cytokines, protease inhibitors, and receptor signaling in cancer." (PMID 39839625, 2024). "Our findings are in line with these reports, demonstrating that EPHB2 can influence migration and invasion also in NSCLC, supporting the notion that this receptor has a pro-oncogenic role also in this cancer type." (PMID 37980331, 2023).
cancer (continued). "Results: 239 genes were identified for further survival analysis, 5 of which were overlapping genes across at least five cancer types, including RHEBL1, PDE4B, ANKRD55, EPHB2, and GIMAP7." (PMID 34262492, 2021). "Our data also revealed a remarkable increase in the levels of phosphorylated EphB2 in GBM cells with C3G downregulation, which promotes migration and invasion of GBM and GBM cancer stem cells." (PMID 33824275, 2021). "In cancer research several clinical trials are conducted with different EPH receptor targeting agents, but for EPHB2, clinical trials are still awaiting." (PMID 32337793, 2020). "From this analysis, 10 commonly regulated genes were identified, and we validated the role of four genes (ENO2, EphB2, SerpinE1, and STX12), which were reportedly involved in cancer cell activities, as downstream targets of NFE2L1." (PMID 32942643, 2020). "EphB3 and EphB2 are reported to be overexpressed in GBM cell lines and to have a pro-tumoral role promoting migration and invasion in cancer cells." (PMID 32764266, 2020). "Once we established that in an exogenous expression system EphB2-Fc promotes the activation of RhoA and cell migration as well as cell invasion through an ephrinB1/RhoGDI1 interaction, we next assessed whether depletion of endogenous ephrinB1 or RhoA influences cancer cell migration and invasion." (PMID 29059157, 2018). "The single-cell transcriptomic analysis further refined this observation by revealing EPHB2’s specific enrichment in malignant cells, supporting its potential as a cancer cell-intrinsic driver rather than a bystander alteration." (PMID 41322437, 2025). "Different works demonstrate an association between phospholipases and Wnt signaling, β-catenin and the Wnt target gene EphB2, TGF-β and Phosphatidylinositol 3-kinase/Protein kinase B (PI3K/Akt) in different cancer tissues, all of them molecular pathways closely linked to tumor processes." (PMID 39596471, 2024). "EPHB2 is located at 1p35-p36.1, a region frequently deleted in CRC and other cancers." (PMID 38651144, 2024). "In addition, some researchers found that EPHB2 kinase expression is elevated in sorafenib-resistant HCC cells, and this kinase regulates cancer stemness and drug resistance through the TCF1/EPHB2/β-catenin positive feedback loop." (PMID 36891274, 2023). "Nevertheless, investigations into the suggested targets, EphB2 and HDAC3, using selective inhibitors might prove fruitful given their implications in other cancers." (PMID 35666359, 2022). "There are also reports that the expression of EPHB2 is reduced during the development of CRC tumors, and its high expression may inhibit the development of tumors and reduce the invasion of cancer cells." (PMID 33937013, 2021). "On the contrary, EPHB2, ERBB4, FGFR1, PDGFRA, KDR, and FLT1 genes showed deletion in cancer cells." (PMID 32038722, 2019). "Furthermore, ephrinB1 depletion by siRNA suppresses EphB2-Fc-induced RhoA activation, and reduces motility and invasiveness of the SW480 and Hs578T human cancer cell lines." (PMID 29059157, 2018). "This revealed three different cancer subsets based on i) enrichment of EPHB2+ cells and lack of ERBB3+ cells, ii) absence of EPHB2+ cells or iii) the presence of both ERBB3+ and EPHB2+ cancer cell populations." (PMID 26367378, 2015). "We determined that EPHB2 has significant interactions with several key proteins, including L1CAM, ABL2, KDM4A, BTF3, and SRC, suggesting that it may form a functional network critical to cancer progression." (PMID 41322437, 2025). "Other studies indicate that the regulatory functions of individual C19MC miRNAs in cancer are related to silencing the expression of factors and signaling pathways related to adhesion, migration, differentiation, growth and angiogenesis (Rap1b, ABCG2, DAPK2, ephrins-EphB2 and EphB4, CXCR4)." (PMID 36430313, 2022). "However, there are no reviews focusing on the dual roles of EphB2 in cancer." (PMID 35223830, 2022).